MATR3 (matrin 3)
Diseases named in the same sentence as MATR3 in open-access papers (continued):
Sharing a sentence is not in itself a finding about the gene and the disease.
infection (7 papers, 2015 to 2025). The state of being infected such as from the introduction of a foreign agent such as serum, vaccine, antigenic substance or organism. "Depletion of the RNAi pathway proteins Dicer, MOV10, TRBP2 and Matrin 3 decreased viral load in infected cells, alluding to an impact of the RNAi pathway in the establishment of a productive infection." (PMID 35893693, 2022). "The interference of CIGB-300 on the virus-infection induced phosphorylation of MATR3 may play a role in reducing its effect on the attenuation of the immune response and its involvement in viral RNA processing." (PMID 34930105, 2021). "Most of them include a step of T cell activation before infection and genes such as those coding for MATR3 and PSF could remain expressed at sublimiting levels also when the HIV-1 provirus returns to the silent state." (PMID 30425153, 2018). "Binding of Matrin 3 to DDX17, EXOSC3, and ZAP in uninfected cells may reflect a role for Matrin 3 in alternate host RNA processes, but during infection Matrin 3 may impede ZAP from interacting with these proteins which are needed for optimal RNA degradation activity." (PMID 26129669, 2015). "Here we show that during infection and reactivation, unspliced HIV-1 RNA is a subject to complex and dynamic regulation by the Rev cofactor MATR3 and the MTR4 cofactor of the nuclear exosome." (PMID 40021667, 2025). "Comparing data collected 24 hours post-infection in each study, four phosphosites were upregulated at least two-fold in four of these studies: HSPB1/HSP27 S15, MATR3 S188, TRIM28/TIF1B/KAP1 S473, and SZRD1 S107." (PMID 37345956, 2023). "Infection with HR’-CMV-luc showed very modest reductions under all conditions tested, demonstrating that Matrin 3 knockdown in the context of ZAP overexpression was not causing a global decrease of newly expressed luciferase reporter." (PMID 26129669, 2015). "This interaction of Matrin 3 with essential components of the RNA degradation machinery was observed in uninfected cells and with no apparent increase following HIV-luc infection." (PMID 26129669, 2015).
cancer (6 papers, 2018 to 2024). A tumor composed of atypical neoplastic, often pleomorphic cells that invade other tissues. "Dysregulation in MATR3 expression has been linked to other diseases, including cancer." (PMID 38891112, 2024). "Taken together, these studies demonstrate that MATR3 dysregulation is associated with cancer, but it may play a different role depending on the cancer type." (PMID 38891112, 2024). "In triple-negative breast cancer (TNBC), high levels of MATR3 promoted apoptosis and inhibited epithelial-mesenchymal transition, migration, and invasion of the cancer cells." (PMID 38891112, 2024). "Determining the role of MATR3 would help identify potential therapeutic targets for various diseases, from neurodegeneration to cancer, and enable development of therapeutic strategies." (PMID 38891112, 2024). "Recent studies have also revealed MATR3’s involvement in other diseases, including cancer, further underscoring the importance in studying the role of MATR3 in various cellular and disease contexts." (PMID 38891112, 2024). "More studies are required to examine why MATR3 plays a differential role in these cancer types as well as to pinpoint the exact mechanisms as to how MATR3 contributes to cancer disease progression." (PMID 38891112, 2024). "In cancer, MATR3 was identified as one of the genes deleted from the chromosome 5 of human BLBC (primary, metastasized, and xenografted in immune-deficient mice) along with CTNNA1, LRRTM2, and SNORA74A." (PMID 32977861, 2020). "In addition to the revelation of its biological role, recent studies have reported MATR3’s involvement in the context of various diseases, including neurodegenerative and neurodevelopmental diseases, as well as cancer." (PMID 38891112, 2024). "However, to date, the biological role and prognostic relevance of MATR3 in human cancers still need to be explored." (PMID 36830863, 2023). "However, the biological role and prognostic relevance of MATR3 in human cancers remain largely under explored." (PMID 36830863, 2023). "We then explored whether MATR3 affects migration and invasion which decide the metastatic nature of the cancer cells." (PMID 32977861, 2020). "Furthermore, recent studies have revealed that MATR3 may play a critical role in other diseases, including cancer." (PMID 38891112, 2024). "In view of the finding that MATR3 is involved in the early response to DNA double-stranded breaks, we hypothesize that disruption of this system may be one possible mechanism by which MATR3 halts cancer progression." (PMID 36830863, 2023). "Moreover, positive mRNA expression of MATR3 was more common in patients without cancer cells in lymph nodes than in those with lymph node metastases (p = 0.01)." (PMID 36830863, 2023).
neuromuscular disease (1 paper, 2021). "Cellular and animal models have been pivotal for our understanding of MATR3-linked neuromuscular disease, and we expect new models to offer further insights." (PMID 33427209, 2021). "MATR3 shares many similarities with other RBPs implicated in neuromuscular disease." (PMID 33427209, 2021). "Mutations in the MATR3-encoding gene are responsible for neuromuscular disease, implying that this protein is critical for maintaining neurons as well as muscle, but how MATR3 mutations affect its function and/or contribute to disease pathogenesis remains unclear." (PMID 33427209, 2021). "This Review will discuss basic MATR3 biology and its functions in nucleic acid processing in the nervous system, clinical evidence tying MATR3 to neuromuscular disease, and insights into MATR3-mediated pathogenesis from model systems and human postmortem tissue." (PMID 33427209, 2021). "We begin by reviewing MATR3’s functions, its regulation, and how it may be involved in both sporadic and familial neuromuscular disease." (PMID 33427209, 2021).
MATR3 also shares sentences with these, for which no sentence is quoted: spinal muscular atrophy (3 papers); autosomal dominant distal myopathy (2); neurologic disease (2); prostate carcinoma (2); adrenocortical cancer (1); aortic coarctation (1); bladder cancer (1); cognitive decline (1); filaminopathy (1); fragile X-associated tremor/ataxia syndrome (1); genetic disorder (1); hereditary spastic paraplegia (1); Huntington disease (1); Hutchinson-Gilford progeria syndrome (1); motor neuron degeneration (1); muscular atrophy (1); myeloma (1); myotilinopathy (1); Paget disease (1); Patent ductus arteriosus (1); prion disease (1); rectal adenocarcinoma (1); renal carcinoma (1); restrictive dermopathy (1); Retina Degeneration (1); Sepsis (1); triple-negative breast carcinoma (1); viral infection (1); vocal cord pharyngeal distal myopathy (1); Welander distal myopathy (1).